POU6F1 (POU class 6 homeobox 1)
Description:
Transcription factor that binds preferentially to a variant of the octamer motif (5'-ATGATAAT-3').
Synonyms: BRN5; MPOU; TCFB1
Gene: Protein-coding gene on chromosome 12 (51,186,936 to 51,218,062, reverse strand). Ensembl gene ENSG00000184271.
Subcellular location: Nucleus
Subcellular location (Human Protein Atlas): Nuclear bodies; Actin filaments
Genetic constraint (gnomAD): Loss-of-function variants: 8 observed, 27.09 expected, observed/expected ratio (o/e) 0.3, 90% interval 0.17 to 0.53. The upper end of that interval is the gene's LOEUF score, 0.53, which puts it in group 2 of 6, group 1 being the genes least tolerant of losing a copy. Missense variants: 315 observed, 424.5 expected, observed/expected ratio (o/e) 0.74, 90% interval 0.68 to 0.81. Synonymous variants: 167 observed, 171.72 expected, observed/expected ratio (o/e) 0.97, 90% interval 0.86 to 1.11.
Homologues: Orthologues: chimpanzee POU6F1 (99% identical), macaque POU6F1 (99% identical), rabbit POU6F1 (95% identical), pig POU6F1 (93% identical), rat Pou6f1 (93% identical), dog POU6F1 (92% identical), mouse Pou6f1 (83% identical), tropical clawed frog pou6f1 (67% identical), zebrafish pou6f1 (58% identical), Caenorhabditis elegans ceh-18 (18% identical), Drosophila melanogaster vvl (15% identical), Drosophila melanogaster acj6 (14% identical), and 1 more. Paralogues in human: POU6F2 (42% identical), POU2F1 (20% identical), POU2F2 (18% identical), POU3F4 (17% identical), POU2F3 (17% identical), POU3F3 (17% identical), POU3F2 (16% identical), POU4F1 (16% identical), POU1F1 (15% identical), POU3F1 (15% identical), POU4F3 (14% identical), POU4F2 (14% identical), and 5 more.
Diseases named in the same sentence as POU6F1 in open-access papers:
POU6F1 is named in the same sentence as 15 diseases in open-access papers, as found by Europe PMC text mining. Sharing a sentence is not in itself a finding about the gene and the disease. The quoted sentences say what the papers report.
lung adenocarcinoma (4 papers, 2022 to 2026). A carcinoma that arises from the lung and is characterized by the presence of malignant glandular epithelial cells. "POU class 6 homeobox 1 (POU6F1) participates in transcriptional regulation, which is closely associated with tumor stage and mortality of lung adenocarcinoma." (PMID 38267746, 2024). "POU6F1 is associated with corticotropin-releasing hormone expression regulation, neuroplasticity and the proliferation of lung adenocarcinoma." (PMID 39020437, 2024). "Although POU6F1 has been unveiled to suppress the growth of lung adenocarcinoma cells, there is no study showing the relationship between POU6F1 and ferroptosis." (PMID 38267746, 2024).
gastric cancer (2 papers, 2024 to 2025). A primary or metastatic malignant neoplasm involving the stomach. "Furthermore, POU6F1 was found to upregulate lncRNA CASC2, leading to reduced GSH levels through increased SOCS2-mediated ubiquitination and degradation of SLC7A11, thereby inducing ferroptosis in gastric cancer (GC) cells." (PMID 40403492, 2025). "This study investigated the effect and mechanism of POU6F1 and lncRNA-CASC2 on ferroptosis of gastric cancer (GC) cells." (PMID 38267746, 2024).
hypogonadism (2 papers, 2024 to 2025). A disorder characterized by decreased function of the gonads. "Both POU6F1 and POU6F2 have been reported to suppress tumor proliferation, and POU6F2 mutations have been implicated in the progression of Wilms tumor, hypogonadism, and pubertal failure in human patients." (PMID 40063068, 2025).
bladder urothelial carcinoma (1 paper, 2022). "Our research revealed that the POU6F1 level was downregulated in various cancers, such as bladder urothelial carcinoma and lung squamous cell carcinoma, etc.." (PMID 35504868, 2022).
brain cancer (1 paper, 2025). A primary or metastatic malignant neoplasm affecting the brain. "Among the other transcription factors that we found among colon transcriptomics features Irx2, Pou4f1, Pou6f1, Tfap2a, Ctdp1, and Msx1 are known to be involved in neuronal development or closely related processes 31–37, and Fubp1 in brain cancer." (PMID 40791429, 2025).
breast carcinoma (1 paper, 2015). "Predicted regulatory element sequences for NANOG, CREB1, CPBP, BEN, PREB-1, SOX10, and POU2F1 (OCT1) POU6F1 and MEIS1 were highly enriched in the promoter regions of the tissue context dependent genes suggesting their possible roles in stem cells proliferation in HER2-regulated breast cancer tissue." (PMID 25428913, 2015).
cholangiocarcinoma (1 paper, 2022). A carcinoma that arises from the intrahepatic biliary tree (intrahepatic cholangiocarcinoma) or from the junction, or adjacent to the junction, of the right and left hepatic ducts (hilar cholangiocarcinoma). "On the contrary, the expression level of POU6F1 was markedly upregulated in cholangiocarcinoma and liver hepatocellular carcinoma." (PMID 35504868, 2022).
clear cell adenocarcinoma (1 paper, 2022). A malignant neoplasm composed of glandular epithelial clear cells. "For instance, POU6F1 siRNA dose-dependently suppressed tumor proliferation in clear cell adenocarcinoma cell lines." (PMID 35504868, 2022).
tumor (6 papers, 2022 to 2026). "In the present study, we identified POU6F1 as a transcription factor, which was closely associated with tumor stage and death by mining a public dataset." (PMID 35504868, 2022). "POU6F1 mRNA expression was analyzed in tumor tissues obtained from 153 patients with NSCLC using quantitative real-time polymerase chain reaction." (PMID 42193061, 2026). "In the study, we determined that upregulation of POU6F1 suppressed tumor proliferation and aggressiveness in vitro and in vivo." (PMID 35504868, 2022). "In the study, we identified that the POU domain, class 6, transcription factor 1 (POU6F1), a member of the POU family of transcription factors, was closely associated with tumor stage and death in LUAD." (PMID 35504868, 2022). "We found that the expression of POU6F1 in LUAD was closely associated with clinical and pathological features, including gender, tumor stage, and N stage." (PMID 35504868, 2022). "In addition, ectopic expression of POU6F1 led to a marked reduction in the growth and tumor weight of subcutaneous xenograft tumors." (PMID 35504868, 2022). "Altogether, POU6F1 or lncRNA-CASC2 can activate SOCS2 signaling to promote ferroptosis and further inhibit tumor growth in nude mouse." (PMID 38267746, 2024). "Western blot results in tumor tissues showed that erastin can increase the expression of SOCS2, but inhibit SLC7A11 and GPX4 expression, which can be further promoted by POU6F1 or lncRNA-CASC2 overexpression." (PMID 38267746, 2024).
cancer (3 papers, 2022 to 2025). A tumor composed of atypical neoplastic, often pleomorphic cells that invade other tissues. "The results suggested that POU6F1 played promoting or suppressive roles in different cancers in a context-specific way." (PMID 35504868, 2022). "To further explore the roles of POU6F1 in various carcinogenesis, we investigated the POU6F1 expression level in multiple human cancers using Oncomine and TIMER." (PMID 35504868, 2022). "Of note, RORA influenced the transcript alternation of target genes and cancer growth induced by the knockdown of POU6F1, indicating the suppressive role of POU6F1/RORA in the progression of LUAD." (PMID 35504868, 2022). "POU6F1 and lncRNA-CASC2, through FMRP, regulate the SOCS2/SLC7A11 signaling axis to modulate ferroptosis in gastric cancer, suggesting a novel mechanism for controlling cancer stem-like cell survival and potentially targeting cancer stemness in this disease." (PMID 40271197, 2025).
adenocarcinoma (1 paper, 2026). A common cancer characterized by the presence of malignant glandular cells. "High POU6F1 expression was significantly associated with younger age (p = 0.027), female sex (p = 0.041), non-smoking status (p = 0.002), adenocarcinoma histology (p = 0.021), and the presence of EGFR mutations (p = 0.038)." (PMID 42193061, 2026).
POU6F1 also shares sentences with these, for which no sentence is quoted: Wilms tumor (2 papers); fibrosarcoma (1); lung squamous cell carcinoma (1); thyroid cancer (1).